CXCL2 (C-X-C motif chemokine ligand 2)
Diseases named in the same sentence as CXCL2 in open-access papers (continued):
Sharing a sentence is not in itself a finding about the gene and the disease.
Allergy (3 papers, 2010 to 2023). An allergy is an immune response or reaction to substances that are usually not harmful. "TNFAIP3 and CXCL2, also related to inflammatory responses, were up-regulated at 55 min after pollen exposure and are known to be regulated in allergic diseases." (PMID 34784380, 2021). "The analysis implicated a number of genes with roles in allergy and inflammation, including pro-inflammatory cytokines (IL1A, IL1B, IL6, IL8 and TNF) and factors involved in immune cell activation and recruitment (SELE, SELL, SELP, ICAM1, CSF2, CSF3, CCL2 and CXCL2)." (PMID 21067579, 2010).
alveolitis (3 papers, 2022 to 2025). "Reflecting the significant reduction in expression of chemokines (CCL3, CCL4, CXCL1, CXCL2, and CXCL10) in the lung, the levels of alveolitis in PKD1mKO at 24 h after the S. rectivirgula exposure was also significantly reduced compared to the levels of alveolitis in WT." (PMID 39464896, 2024). "Importantly, CD4 depletion in CoMtb mice completely reversed alveolitis formation and resulted in necrotic granulomas with large central aggregates of neutrophils expressing CXCL2, similar to primary granulomas observed without CoMtb." (PMID 40736456, 2025).
colon adenocarcinoma (3 papers, 2005 to 2023). "In colon adenocarcinoma, CXCL1, CXCL2, and CXCL3 negatively correlated with EMT, while CXCL5, CXCL6, PPBP, and CXCL8 positively correlated with EMT." (PMID 37686093, 2023). "For example, in colon adenocarcinoma, the expression of CXCL1, CXCL2, and CXCL3 negatively correlated with EMT, whereas the expression levels of CXCL5, CXCL6, PPBP, and CXCL8 positively correlated with EMT." (PMID 37686093, 2023).
E. coli infection (3 papers, 2019 to 2022). "Up-regulation of interleukin (Il)-1β, Il-6, Il-8, Il-18, tumor necrosis factor alpha, and chemokine Cxcl2 expression after E. coli infection was attenuated by L. johnsonii L531." (PMID 32823867, 2020). "Similar profile of changes was observed in Tnf-α and Cxcl2 mRNA expression during E. coli infection." (PMID 32823867, 2020). "Our results showed that pretreatment with different doses of L. plantarum 17–5 reduced the expression of IL1β, IL6, IL8, TNFα, COX2, iNOS, CXCL2 and CXCL10 during E. coli infection." (PMID 35764986, 2022).
gastrointestinal stromal tumor (3 papers, 2015 to 2025). "M2-TAMs in gastrointestinal stromal tumors (GIST) were observed to secrete CXCL2, enhancing the migration, invasion, and EMT of GIST cells via the CXCL2-CXCR2 signaling pathway." (PMID 40959082, 2025). "Among them, CXCL2 was found to be secreted by M2-TAM in gastrointestinal stromal tumor TMEs and led to tumor metastasis." (PMID 38546390, 2024).
glomerulonephritis (3 papers, 2018 to 2024). A renal disorder characterized by damage in the glomeruli. "Inflammatory processes in glomerulonephritis strongly depend on the pro-inflammatory chemokines CXCL8 (interleukin-8 (IL-8)), CCL2 (monocyte chemotactic protein-1 (MCP-1)) and CXCL2 (macrophage inflammatory protein-2α (MIP-2α)) to direct neutrophils and macrophages towards the glomerulus." (PMID 30248108, 2018).
Hepatitis (3 papers, 2017 to 2026). Inflammation of the liver. "Recently, we reported that orphan nuclear receptor small heterodimer partner (SHP) is involved in neutrophil recruitment through the regulation of C-X-C motif chemokine ligand 2 (CXCL2) expression in a concanavalin A (ConA)-induced hepatitis model." (PMID 30323351, 2018). "We observed that SHP deficiency in hepatocytes led to the increased secretion of CXCL2, but not CXCL1, upon TNFα stimulation, emphasizing that hepatocytes contribute to increased levels of circulating CXCL2 in Shp KO mice during ConA-induced hepatitis." (PMID 30323351, 2018). "Collectively, we demonstrated that CXCL2-derived neutrophils are critical mediators of experimental hepatitis." (PMID 30323351, 2018). "Infiltrating neutrophils to the injured liver, driven by CXCL2, were also significantly increased in KO recipient mice regardless of WT or Shp KO donor, suggesting that SHP deficiency in liver parenchymal cells is critical for ConA-induced hepatitis." (PMID 30323351, 2018). "The liver transcriptional expressions of CXCL1, CXCL2, CXCL3, CXCL5, CCL2, and CCL6 significantly increased in WT and IL-33 KO mice during L2-MHV3-induced hepatitis compared to those in control PBS-injected mice as soon as 48 h PI and at 72 h PI." (PMID 28607531, 2017).
leukemia (3 papers, 2013 to 2024). A malignant (clonal) hematologic disorder, involving hematopoietic stem cells and characterized by the presence of primitive or atypical myeloid or lymphoid cells in the bone marrow and the blood. "Furthermore, HSC-prog cells showed more interactions with other cells through known ligand–receptor pairs, such as leukaemia-associated ligands CXCL2, CXCL3, and FLT3, signalling to the receptors CXCR1 and CXCR2 expressed by CD14-mono and NK cells." (PMID 37615858, 2024).
Listeria infection (3 papers, 2010 to 2025). "Although RelA/p65-mediated Cxcl-2 production exhibited a slower kinetic as compared to following Listeria infection, a significant number of Cxcl-2+ cells was detected." (PMID 21124989, 2010). "In a model of Listeria monocytogenes infection, IFNγ downregulates expression of CXCR2 (the only receptor for CXCL2 in mice) on neutrophils, thereby curtailing their recruitment to the site of inflammation." (PMID 30012158, 2018). "Importantly, downregulation of Nox4 expression in epithelial cells by siRNA interference significantly reduced Cxcl-2 secretion and ROI production upon Listeria-infection." (PMID 21124989, 2010). "Inhibition of gap junctional intercellular communication, however, did not decrease the number of activated epithelial cells after Listeria infection as illustrated by the unaltered high ratio of activated (Cxcl-2+) to infected (GFP+) epithelial cells measured by flow cytometry." (PMID 21124989, 2010).
liver disease (3 papers, 2014 to 2024). "Literature and data mining found abnormal induction of chemokine (C-X-C motif) ligand 1 (CXCL1) and CXCL8 and down-regulation of CXCL2 in inflammatory liver diseases." (PMID 39619227, 2023). "This dual role highlights the intricate balance between inflammatory processes and tissue repair mechanisms in liver diseases, emphasizing the multifaceted nature of MIP-2/Cxcl2 in liver pathophysiology." (PMID 38229193, 2024). "However, the overall GR trend seems to be restorative in liver cells, selectively limiting the inflammatory overexpression of CXCL1 and CXCL8 while simultaneously sparing CXCL2, which is downregulated in various liver diseases but may be crucial for hepatic health." (PMID 39619227, 2023).
myocardial ischemia (3 papers, 2015 to 2021). A disorder of cardiac function caused by insufficient blood flow to the muscle tissue of the heart. "Among the top-regulated and down-regulated genes, some genes described in previous studies were associated with myocardial ischemia and they were significant up-regulated, including Cxcl2 and Il6." (PMID 26540270, 2015). "The role of Cxcl2 and Smad1 in myocardial ischemia also have been reported." (PMID 34238326, 2021).
oral squamous cell carcinoma (3 papers, 2015 to 2024). "Porphyromonas gingivalis induces CXCL2, promoting inflammation and oral squamous cell carcinoma progression." (PMID 39199704, 2024). "For instance, CXCL1, CXCL2, CXCL8, and CCL5 are all related to the progression and diagnosis of oral squamous cell carcinoma." (PMID 39199704, 2024). "Moreover, oral squamous cell carcinoma cell lines, including HSC2, respond to inflammatory cytokines IL1β and TNFα with an increased chemokine expression, including CXCL1, CXCL2, CXCL8, and CCL5." (PMID 39199704, 2024). "Moreover, oral squamous cell carcinoma cell lines, including HSC2, respond to inflammatory cytokines IL1β and TNFα with an increased expression of chemokines such as CXCL1, CXCL2, CXCL8, and CCL5." (PMID 39199704, 2024).
osteoarthritis (3 papers, 2010 to 2025). A noninflammatory degenerative joint disease occurring chiefly in older persons, characterized by degeneration of the articular cartilage, hypertrophy of bone at the margins and changes in the synovial membrane. "In this study, we identified and validated four differentially expressed genes (CXCL8, CXCL2, DUSP5, and TNFSF11) as promising diagnostic biomarkers for osteoarthritis (OA), which collectively mediate immune regulation, inflammatory responses, and bone remodeling in OA pathogenesis." (PMID 40672822, 2025). "CXCL2 that has function in immune response is over-expressed in osteoarthritis fibroblasts rather than rheumatoid fibroblasts, up-regulated in psoriatic epidermis, and also in epithelial tissue." (PMID 20444268, 2010).
plaque psoriasis (3 papers, 2021 to 2024). "Higher expression of neutrophil chemokines, including CXCL1, CXCL2, and CXCL8, were observed in GPP patients compared with plaque psoriasis patients." (PMID 38378928, 2024).
pneumococcal pneumonia (3 papers, 2011 to 2022). A febrile disease caused by STREPTOCOCCUS PNEUMONIAE. "Type I IFNs can inhibit chemokine (e.g. CXCL1 and CXCL2) expression and thereby reduce recruitment of neutrophils to the site of infection in case of secondary pneumococcal pneumonia." (PMID 21625574, 2011). "Additionally, it would be useful to determine which subset of pulmonary cells are expressing Cxcl1, Cxcl2 and Csf3, as this may yield a focused therapeutic target to improve health outcomes in alcohol consumers with pneumococcal pneumonia." (PMID 35603143, 2022).
prostatitis (3 papers, 2015 to 2025). An infectious or non-infectious inflammatory process affecting the prostate gland. "Moreover, CXCL1 and CXCL2 were enhanced in Gr(+)-sorted neutrophils infiltrating the gland in the LPS-induced prostatitis model as well as in LPS-elicited peritoneal cells from animals treated with testosterone." (PMID 30233581, 2018).
renal clear cell carcinoma (3 papers, 2021 to 2023). "The protein concentration of CXCL2 in the extracellular medium of renal clear cell carcinoma has been identified as an important factor contributing to cancer development." (PMID 37540227, 2023). "CXCL2 also had survival value in six cancers (P < 0.05), especially in renal clear cell carcinoma (P = 0.003)." (PMID 37540227, 2023). "The EMT pathway, as analyzed through GSVA in KIRC, was verified to be a key mechanism by which CXCL2 regulated renal clear cell carcinoma cells." (PMID 37540227, 2023). "Furthermore, CXCL2 can promote the growth, penetration, and movement of renal clear cell carcinoma cells in a laboratory setting through the activation of the EMT process." (PMID 37540227, 2023). "Considering that CXCL2 promoted the progression of renal clear cell carcinoma via inducing activation of the EMT process, we added the EMT pathway inhibitor (EMT inhibitor-1, 10 uM/mL, product ID: HY-101275) to the medium containing 100 ng/mL of human recombination CXCL2 protein (EMT group)." (PMID 37540227, 2023). "Moreover, our results revealed that CXCL2 promoted renal clear cell carcinoma progression through multiple mechanisms." (PMID 37540227, 2023). "In addition, a previous study showed a four immune-related genes signature based on CXCL2, SEMA3G, PDGFD, and UCN is closely associated with the prognosis of renal clear cell carcinoma." (PMID 34030645, 2021).
tuberculosis (3 papers, 2016 to 2023). A chronic, recurrent infection caused by the bacterium Mycobacterium tuberculosis. "Furthermore, the expression of CCL20, CXCL8 and CXCL2 has been implicated in the pathogenesis of tuberculosis." (PMID 33057074, 2020).
ulcerative colitis (3 papers, 2015 to 2025). An inflammatory bowel disease involving the mucosal surface of the large intestine and rectum. "Previous studies have demonstrated that the expression of CCL9, CXCL1, and CXCL2 is significantly increased in the colonic epithelial cells of experimental colitis mice and ulcerative colitis (UC) patients." (PMID 39896755, 2025). "Interestingly, CXCL2 has been found upregulated in inflamed mucosa compared to not inflamed mucosa of patients with ulcerative colitis, a condition that increases the risk of CRC." (PMID 32676506, 2020).
anemia (2 papers, 2022 to 2024). A reduction in the number of red blood cells, the amount of hemoglobin, and/or the volume of packed red blood cells. "Blood gas analysis showed dilutional anemia during V-V ECMO, whereas plasma analysis revealed a decreased concentration of IL-10 during V-V ECMO therapy, and BAL measurements showed increased concentrations of TNF-α, CXCL2, and CXCL5." (PMID 38928327, 2024).
bacterial meningitis (2 papers, 2015 to 2016). Inflammation of the membranes surrounding the brain and spinal cord due to a bacterial infection. "Additionally, pyroptosis causes the excessive production of cytokines and chemokines including TNF-α, IL-1β, IL-6, CCL3, CXCL-1, CXCL-2, etc. in bacterial meningitis which can also result in inflammatory mediator-induced neuronal damage." (PMID 26683708, 2015).
breast invasive carcinoma (2 papers, 2017 to 2023). "In breast invasive carcinoma, among the CXCR2 ligands, only CXCL2 inhibits proliferation, and this chemokine was the only one among those analyzed that was negatively correlated with the count of macrophages." (PMID 37686093, 2023). "This possibility was supported by significant upregulation of IL8 receptors (CXCL1 and CXCL2) in clinical invasive breast cancer samples but not in normal controls." (PMID 28703802, 2017).
Chronic colitis (2 papers, 2019 to 2022). A chronic inflammatory disease of the large intestine (colon, cecum and rectum). "In contrast, B. lactis LA804 which was less efficacious in the acute model was the most protective against chronic colitis by downregulating the expression of genes for CXCL2, IL-1β and TNF-α in TNBS-treated mice." (PMID 31035617, 2019).
Cognitive impairment (2 papers, 2019 to 2022). Abnormal cognition is characterized by deficits in thinking, reasoning, or remembering. "Additionally, previous studies found that the abundance of pro-inflammatory Escherichia/Shigella in stool was higher in patients with cognitive impairment and brain amyloidosis than in the control group, and was positively related to the level of IL-1β, CXCL2 and NLRP3 inflammasome." (PMID 36405958, 2022).
contact dermatitis (2 papers, 2024 to 2025). An inflammatory skin condition caused by direct contact between the skin and either an irritating substance or an allergen. "Dermal infiltrated Ly6C+ monocytes not only express TNF-α but also directly express high-level CXCL2 to mobilize NTEM in contact dermatitis." (PMID 40185981, 2025).
cryptococcal infection (2 papers, 2025). "Both CXCL1/KC and CXCL2/MIP-2α have been observed in cryptococcal infections." (PMID 40666971, 2025). "Indeed, during cryptococcal infection, alveolar macrophages are the predominant producers of CXCL2/MIP-2α, as demonstrated in CXCL2-GFP reporter mice, where these cells exhibited the highest CXCL2 expression within the first 48 hours following C. neoformans infection." (PMID 41357248, 2025). "Additionally, both CXCL1/KC and CXCL2/MIP-2α have been observed in cryptococcal infections." (PMID 41357248, 2025).
encephalitis (2 papers, 2011 to 2018). An acute inflammatory process affecting the brain parenchyma. "In the JE model, the severity of encephalitis is related to skewing of the specific cellular response from regulatory (Treg) to Th17-type, with the increased IL-17, CXCL1, and CXCL2 expression promoting the CNS infiltration by granulocytes, monocytes, and cytotoxic CD8+ lymphocytes." (PMID 29678185, 2018).
Erythema (2 papers, 2023 to 2025). Redness of the skin, caused by hyperemia of the capillaries in the lower layers of the skin. "In addition, 7-methoxyisoflavone has been reported to significantly suppress CXCL1, CXCL2, and CXCL3 expression in both FITC- and oxazolone-induced AD models, which was associated with reduced neutrophil infiltration and attenuated skin erythema and edema." (PMID 40918538, 2025). "Among them, C-X-C motif chemokine ligand 1 and 2 (CXCL1 and CXCL2) are significantly upregulated in lesional skin and primarily mediate neutrophil recruitment through interaction with the CXCR2 receptor, thereby aggravating tissue damage and acute symptoms such as erythema and edema." (PMID 40918538, 2025).
Fulminant hepatitis (2 papers, 2018 to 2021). Acute hepatitis complicated by acute liver failure with hepatic encephalopathy occurring less than 8 weeks after the onset of jaundice. "Here, using bone marrow chimeric mice, we verified that SHP is a previously unrecognized transcriptional regulator of hepatic CXCL2 that contributes to the pathogenesis of fulminant hepatitis." (PMID 30323351, 2018).
gastric tumor (2 papers, 2022 to 2025). "We also note that the expression of several angiogenesis-related genes (Cxcl1, Cxcl2, Mmp2, Mmp9, and Vegf) was comparable among gastric tumor and non-tumor tissues from 3mo and 6mo gp130F/F and gp130F/F:Nlrp3-/- mice." (PMID 35299732, 2022).
helminth infection (2 papers, 2015 to 2020). "The finding that FcRg deficient mice showed a stronger reduction in chemokine levels during helminth infection further supports a role for dectin-2/ FcRg chain triggered CXCL2/3." (PMID 25806513, 2015). "We further show that Fcrg-chain-signaling triggered the release of CXCL2 from MΦ and intestinal MF during helminth infection." (PMID 25806513, 2015). "To clarify if MF represent a potential additional source of CXCL2/3 during helminth infection, we isolated small intestinal MF and performed co-cultures with helminth larvae in the absence or presence of IS." (PMID 25806513, 2015). "Thus, surface IgG receptors likely play an important role in triggering CXCL2 release by MΦ during helminth infection." (PMID 25806513, 2015). "Interestingly, CXCL2 expression in lesions of Fcrg-/- mice was significantly reduced as compared to that in Aid-/- lesions, suggesting that antibody independent but FcRg chain dependent signaling events might contribute to CXCL2 production during helminth infection in vivo." (PMID 25806513, 2015). "As CXCL2 and CXCL3 have been reported to promote repair processes, including smooth muscle cell migration, we investigated the expression of these chemokines during helminth infection in vivo." (PMID 25806513, 2015). "Although these chemokines were not induced in macrophages in response to helminth larvae and immune serum, our data does not rule out a contribution of CXCR2 ligands other than CXCL2/3 to lesion contraction during helminth infection in vivo." (PMID 25806513, 2015). "Although we only detected low levels of CXCL2/3 following primary helminth infection, our study does not rule out a role for antibodies or CXCL2/3 in promoting tissue repair in the absence of immunological memory." (PMID 25806513, 2015). "In this study, eosinophil numbers in the skin after allergen challenge were not affected by helminth infection, however, their production of the neutrophil chemoattractants CXCL1 and CXCL2 were, and this resulted in a greatly reduced neutrophil influx." (PMID 32508831, 2020).
herpesvirus infection (2 papers, 2022). "The pathway category Kaposi sarcoma-associated herpesvirus infection was enriched by two hub-DEGs (ZFP36 and CXCL2)." (PMID 35277538, 2022). "The other significant pathways are Kaposi’s sarcoma-associated herpesvirus infection (steered by ZFP36 and CXCL2), PI3K-Akt signaling pathway and the proteoglycans in cancer pathways (steered by IGF2 and TLR2)." (PMID 35277538, 2022).